CSNK2A2IP (casein kinase 2 subunit alpha' interacting protein)
Description:
May play a role in chromatin regulation of male germ cells.
Synonyms: CSNKA2IP
Gene: Protein-coding gene on chromosome 3 (88,338,416 to 88,467,594, forward strand). Ensembl gene ENSG00000283434.
Subcellular location: Nucleus
Gene Ontology:
Cellular component: nucleus
Genetic constraint (gnomAD): Missense variants: 369 observed, 393.37 expected, observed/expected ratio (o/e) 0.94, 90% interval 0.86 to 1.02. Synonymous variants: 150 observed, 153.19 expected, observed/expected ratio (o/e) 0.98, 90% interval 0.86 to 1.12.
Homologues: Orthologues: chimpanzee CSNKA2IP (95% identical), macaque CSNKA2IP (86% identical), rat Csnka2ip (45% identical), mouse Csnk2a2ip (44% identical).